C5 (complement C5)
Diseases named in the same sentence as C5 in open-access papers (continued):
Sharing a sentence is not in itself a finding about the gene and the disease.
Achalasia (1 paper, 2023). A disorder of esophageal motility characterized by the inability of the lower esophageal sphincter to relax during swallowing and by inadequate or lacking peristalsis in the lower half of the body of the esophagus. "In the current study, complement C1q, C1s, C2, C3, C4-A, C4-B, C5, C6, and C9 were all upregulated in the achalasia group." (PMID 37324545, 2023).
adenoma (1 paper, 2020). A neoplasm arising from the epithelium. "H&E staining showed that adenoma formation was accompanied by diffuse immune cells infiltration in the colons of WT, C3-deficient, and C5ar2-deficient mice, while more mucosa-associated lymphoid tissues suspected as tumors were observed in C5- and C5ar1-deficient mouse colons." (PMID 32754267, 2020).
amyotrophic lateral sclerosis (1 paper, 2025). Amyotrophic lateral sclerosis (ALS) is a neurodegenerative disease characterized by progressive muscular paralysis reflecting degeneration of motor neurons in the primary motor cortex, corticospinal tracts, brainstem and spinal cord. "What is the effect of zilucoplan, an inhibitor of complement C5, in amyotrophic lateral sclerosis (ALS)?" (PMID 39960672, 2025).
autoimmune hemolytic anemia (1 paper, 2018). Autoimmune hemolytic anemia (AIHA) is an autoimmune disorder in which various types of auto-antibodies are directed against red blood cells causing their survival to be shortened and resulting in hemolytic anemia. "Intriguingly, it has been shown in an experimental mouse model of autoimmune hemolytic anemia that C5aR activation does not necessarily involve C5 and C5a." (PMID 29892280, 2018).
autoimmune polyendocrinopathy-candidiasis-ectodermal dystrophy (1 paper, 2022). "The other patients had Kabuki syndrome, Di-George Syndrome, autoimmune polyendocrinopathy-candidiasis-ectodermal dystrophy (APCED), complement C5 deficiency, hyper IgE syndrome, Wiskott-Aldrich, Good syndrome, activated PI3K Delta Syndrome and a homozygous IFN gamma R1 mutation." (PMID 36479106, 2022).
B-cell lymphoma (1 paper, 2025). "The C5 sdAb was selected using an in vivo phage display selection approach in a xenograft mouse model of canine B-cell lymphoma." (PMID 40256602, 2025). "To this end, we fused the truncated PE38 toxin domain derived from Pseudomonas aeruginosa exotoxin A with a rabbit-derived sdAb, termed C5, which we recently developed and characterized for canine B-cell lymphoma." (PMID 40256602, 2025). "In the present study, we developed a recombinant immunotoxin using the C5 sdAb, a promising rabbit-derived sdAb antibody targeting canine B-cell lymphoma, previously developed by our group." (PMID 40256602, 2025).
bacteremia (1 paper, 2018). "In clear contrast to the response of C5-deficient mice, the mice lacking C5aR1 displayed significantly higher survival rates and lower levels of bacteremia than WT mice under conditions of infection with 105 CFU." (PMID 29362231, 2018).
bone marrow failure (1 paper, 2025). "Crovalimab is unique in that it has a longer biological half-life than other C5 inhibitors and can be administered by subcutaneous injection, although the efficacy of the novel complement inhibitor crovalimab in bone marrow failure-associated PNH is more unclear." (PMID 40539183, 2025). "Crovalimab's sustained C5 inhibition (t1/2=53.1 days vs. eculizumab's 187.7 hours) might lead to platelet recovery and suggest the beneficial role of crovalimab in treating bone marrow failure-associated PNH." (PMID 40539183, 2025). "While C5 inhibitors, such as eculizumab and ravulizumab, have transformed PNH management, optimal strategies for bone marrow failure-associated PNH remain unclear." (PMID 40539183, 2025). "Since there have been no other findings to show that crovalimab, a novel subcutaneous C5 inhibitor, improves platelet counts, a registry study of crovalimab-treated PNH patients with bone marrow failure is warranted." (PMID 40539183, 2025).
Brain atrophy (1 paper, 2024). Partial or complete wasting (loss) of brain tissue that was once present. "Preliminary analyses in different cognitive groups demonstrated that the reduced CSF complement peptides C1q, C2, C5, and CFB were associated with longitudinal brain atrophy (i.e., ventricles, whole brain, middle temporal lobe, or fusiform gyrus) and cognitive decline in MCI participants." (PMID 38238858, 2024).
breast tumors (1 paper, 2022). "Mouse cytokine profiling revealed that compared to vehicle controls, SI-2 treatment significantly increased the levels of complement component 5 (C5)/C5a and interleukin 1 receptor antagonist (Il-1ra) in E0771 breast tumors." (PMID 36316775, 2022).
bullous pemphigoid (1 paper, 2018). Bullous pemphigoid (BP) is the most common form of autoimmune bullous dermatosis. "It has been demonstrated that an experimental model of bullous pemphigoid cannot be induced in mice deficient of the key complement component C5." (PMID 30473747, 2018). "We therefore hypothesized that loss of CD55, a typical complement regulator acting via suppression of C3 and C5 activity, contributes to bullous pemphigoid development." (PMID 30473747, 2018). "In addition, it has been reported that complement component C5-deficient mice do not develop bullous pemphigoid following exposure to the pathogenic anti-BP180 IgG, which is used to induce this disease model." (PMID 30473747, 2018).
chronic myelomonocytic leukemia (1 paper, 2022). A myelodysplastic/myeloproliferative neoplasm which is characterized by persistent monocytosis, absence of a Philadelphia chromosome and BCR/ABL fusion gene, fewer than 20 percent blasts in the bone marrow and blood, myelodysplasia, and absence of PDGFRA or PDGFRB rearrangement. "The terminal complement inhibitor Eculizumab (anti-C5) has been used as rescue therapy of AIHA in a patient with Waldenström macroglobulinemia and in a patient with chronic myelomonocytic leukemia (CMML)." (PMID 36052091, 2022).
cognitive decline (1 paper, 2024). "Besides, our study found that neuroimaging markers might mediate the associations between CSF complement proteins (C1q, C2, C5, CFB and clusterin) and cognitive decline." (PMID 38238858, 2024). "The direct impact of reduced CSF complement peptides C1q, C2, C5, and CFB on cognitive decline was also observed in the MCI participants." (PMID 38238858, 2024).
crescentic glomerulonephritis (1 paper, 2016). A histopathologic term for a pattern of diseases characterized by extensive crescent formation in the glomeruli; patients present clinically with rapid deterioration of renal function, and possible progression to end-stage renal failure within weeks or months. "Histological measures of disease showed that crescentic glomerulonephritis was more severe in both groups of C5‐sufficient recipients, compared with both groups of C5‐deficient recipients, as indicated by more crescents and CD68+ macrophages within glomeruli." (PMID 27235854, 2016).
cysticercosis (1 paper, 2011). "We have demonstrated that C5 underlies the Tccr1 locus and uncovered an important role of the complement pathway in susceptibility to T. crassiceps cysticercosis." (PMID 22206032, 2011).
endophthalmitis (1 paper, 2024). An infectious process affecting the internal structures of the eye. "C5 inhibition might have a potentially lower risk of endophthalmitis, preserving C3-associated effector functions, such as C3b-mediated opsonization and immune cell activation, compared to an upstream C3 blockade, which also abrogates C3b effects." (PMID 39338244, 2024).
erythroderma desquamativum (1 paper, 2025). "For instance, infants with a C5 complement deficiency may develop Leiner disease, or erythroderma desquamativum, which manifests as recurrent diarrhea, wasting, and generalized seborrheic dermatitis." (PMID 40422242, 2025).
fibrosarcoma (1 paper, 2016). A malignant mesenchymal fibroblastic neoplasm affecting the soft tissue and bone. "But complement C5 also aided the more distal steps of the metastasis process, by allowing extravasation of fibrosarcoma cells into the lung, or by altering the immune cell environment of the metastatic target organ." (PMID 27105526, 2016).
fibrosis (1 paper, 2017). the formation of excess fibrous connective tissue in an organ or tissue in a reparative or reactive process. "It was reported that small molecule inhibitors of the C5a receptor had antifibrotic effects in vivo, and common haplotype-tagging polymorphisms of the human gene C5 were associated with advanced fibrosis in chronic hepatitis C virus infection." (PMID 27605044, 2017).
fungal meningitis (1 paper, 2023). Meningitis caused by fungal agents which may occur as opportunistic infections or arise in immunocompetent hosts. "Therefore, we chose a model well-known for its utility in studying fungal meningitis: the C5-complement-deficient mouse strain A/J." (PMID 38010145, 2023).
gastric cancer (1 paper, 2024). A primary or metastatic malignant neoplasm involving the stomach. "So, we speculate that complement C5/C5aR can regulate iron metabolism in gastric cancer through regulation macrophages polarization and LCN2 expression." (PMID 39850877, 2024).
glomerulosclerosis (1 paper, 2024). A hardening of the kidney glomerulus caused by scarring of the blood vessels. "Our case series emphasizes that a diagnosis of WT1 mutation can be considered in children with aHUS with severe renal manifestations without a response to C5 inhibitors and with global glomerulosclerosis on renal biopsy." (PMID 39445256, 2024).
heart failure (1 paper, 2025). Inability of the heart to pump blood at an adequate rate to meet tissue metabolic requirements. "Indeed, several studies have shown that blocking the complement system with anti-C5 antibodies can enhance outcomes in heart failure, particularly in cases of antibody-mediated rejection following heart transplantation (43, –, 45)." (PMID 39846741, 2025).
hemophilia A (1 paper, 2025). The most common form of hemophilia characterized by spontaneous or prolonged hemorrhages due to factor VIII deficiency. "In benign hematology, the advent of FcRn inhibitors, recycling of C5 antibodies, and FVIII-mimetic bispecifics has further expanded the reach of antibody therapeutics beyond oncology, improving outcomes in ITP, PNH, aHUS, and hemophilia A." (PMID 41511330, 2025).
hepatoma (1 paper, 2014). "In addition, HCV inhibits C5 mRNA synthesis in hepatoma cells." (PMID 24983375, 2014).
Hypoglycemia (1 paper, 2021). A decreased concentration of glucose in the blood. "Complement C5 decreased in controls only at 2-h post-hypoglycemia versus baseline (p < 0.05)." (PMID 36643727, 2021).
immunodeficiencies (1 paper, 2025). "Despite these challenges, our study represents a significant step forward in understanding C5 deficiency and its role in complement-related immunodeficiencies." (PMID 40692790, 2025).
infarction (1 paper, 2017). A localised pathological necrosis of tissue resulting from obstruction of the blood supply usually by a thrombus, an embolus, or vascular torsion. "In conclusion, we show in this clinically relevant model of myocardial IRI that complement inhibition of C5 reduces infarction size, possibly through reduction of IL-1β and E-selectin, and improves ventricular function." (PMID 28258298, 2017).
iron overload (1 paper, 2025). "Men and patients with a high transfusion burden may be at a greater risk for iron overload when treated with C5 inhibitors compared with women and those with a low transfusion burden." (PMID 41155315, 2025). "Our findings identify iron overload in C5 inhibitor–treated patients with PNH." (PMID 41155315, 2025). "However, several previous publications have reported just the opposite (i.e., iron overload) following PNH treatment with the C5 inhibitor eculizumab." (PMID 41155315, 2025). "In an analysis of 5 patients with PNH who received C5 inhibitors, all patients had high concentrations of ferritin, an iron storage protein and marker of iron overload, after C5 inhibitor treatment, with some manifesting increased hepatic iron on magnetic resonance imaging (MRI)." (PMID 41155315, 2025). "Although C5 inhibitors alleviate most of the IVH and iron loss, the ongoing transfusion needs that persist could cause transfusional iron overload and iron retention in the hepatocytes and Kupffer cells of the liver." (PMID 41155315, 2025).
ischemia reperfusion injury (1 paper, 2017). Adverse functional, metabolic, or structural changes in ischemic tissues resulting from the restoration of blood flow to the tissue (reperfusion), including swelling; hemorrhage; necrosis; and damage from free radicals. "Complement activation, C5 cleavage and release of fraction C5a have been widely implicated in the inflammatory response to ischemia-reperfusion injury." (PMID 28832655, 2017).
Jaundice (1 paper, 2023). Yellow pigmentation of the skin due to bilirubin, which in turn is the result of increased bilirubin concentration in the bloodstream. "Tonack and collaborators have also looked for potential plasma biomarkers for PDAC and found some candidates, but they are associated with jaundice, showing the highest sensitivity of ITIH3, C5, A1BG, PIGR, and Reg3A in this condition." (PMID 37628784, 2023).
kidney stone (1 paper, 2023). "C3 and C5 inhibitors might contribute to attenuate the complement-driven inflammation in kidney stone formation and recurrence." (PMID 36932340, 2023).
kidney transplant (1 paper, 2022). A surgical procedure in which one or both kidneys from a donor are implanted into a recipient. "In pediatric kidney transplant recipients, C5 inhibition with eculizumab prior to graft reperfusion was shown to improve early graft function, graft morphology and early graft survival indicating a reduction in IRI." (PMID 35432333, 2022).
liver failure (1 paper, 2022). A liver disease characterized by the liver losing or has lost all of its function. "In a mouse 70% partial hepatectomy model, C3- and C5-deficient mice succumb to liver failure, a phenotype rescued by the reconstitution of effector molecules C3a and C5a." (PMID 36341433, 2022).
lymphopenia (1 paper, 2020). Reduction in the number of lymphocytes. "The factors that contribute to the state of hyperinflammation are persistent lymphopenia, neutrophilia, over-activation of complement components C3, C3a, C5, C5a and mannose binding lectin-associated serine protease (MASP2); in addition to the cytokine storm." (PMID 33708109, 2020).
macular degeneration (1 paper, 2021). Loss of vision in the central portion of the retina (macula), secondary to retinal degeneration. "To address this need, in this study we have used mouse and cell-based models of macular degeneration to investigate the role of C5 in the formation of sub-RPE deposits." (PMID 34001980, 2021).
mastitis (1 paper, 2021). Inflammation of breast tissue during lactation or postpartum due to an obstructed duct or infection. "Many mastitis associated genes like complement C5 (C5) and chemokine (C-X-C motif) receptor 1 (CXCR1), are reported to be conserved as high as up to 99% sequence similarity." (PMID 34222390, 2021).
meningioma (1 paper, 2014). A generally slow growing tumor attached to the dura mater. "Comparative serum proteomic analysis of healthy subjects and meningioma patients indicated activation of complement cascades in meningiomas with up-regulation of quite a few complement factors including C5, C8 beta chain, C6, C4-B." (PMID 25413266, 2014).
metastatic disease (1 paper, 2016). "RT2 AB6F2 animals encoding two nonfunctional alleles of complement C5 had a significantly lower frequency of liver metastatic disease than animals encoding one or more functional copies of the gene." (PMID 27105526, 2016). "Thus both genetic and pharmacological evidence link complement C5 to liver metastatic disease in RT2 mice." (PMID 27105526, 2016).
Miller Fisher syndrome (1 paper, 2016). An autoimmune process characterized by the clinical triad of ophthalmoplegia, ataxia, and areflexia. "Recently, C5 complement component inhibitors that block the formation of the membrane attack complex and subsequent downstream injury have been shown to be efficacious in an in vivo anti-GQ1b antibody-mediated mouse model of the GBS variant Miller Fisher syndrome (MFS)." (PMID 26936605, 2016).
myocardial ischemia (1 paper, 2023). A disorder of cardiac function caused by insufficient blood flow to the muscle tissue of the heart. "A study found that degenerative necrotic tissue cells after myocardial ischemia were enriched in the complement and coagulation cascade pathway, and complement system activation products such as C3, C4, and C5 played a major role in myocardial ischemia-reperfusion inflammatory injury." (PMID 37965086, 2023).
myopia (1 paper, 2025). "This study highlights the role of TGF-β2 in promoting myopia through the activation of complement components C3 and C5 and suppression of CD55, leading to enhanced inflammasome activity." (PMID 40862775, 2025). "Results showed that TGF-β2 exacerbated myopia by upregulating complement components C3 and C5, suppressing CD55, and activating inflammasome pathways through nuclear factor (NF)-κB signaling, leading to axial elongation and increased refractive errors." (PMID 40862775, 2025).
nasopharyngeal carcinoma (1 paper, 2014). A carcinoma arising from the nasopharyngeal epithelium. "A significant association of CR2 SNP (rs3813946) with the development of nasopharyngeal carcinoma was indicated in Cantonese population, and the genetic variations of complement system genes C5 and C9 plays a potential role in susceptibility to non-Hodgkin lymphoma (NHL)." (PMID 24621201, 2014).
neuroblastoma (1 paper, 2023). Neuroblastoma (NB) is the most common solid, extracranial childhood tumor. "There was constitutive expression of complement factor B, C3, C5 and C9 in SH-SY5Y neuroblastoma cell lines stably expressing the NOTCH3 receptor." (PMID 37158955, 2023).
neuropathies (1 paper, 2021). "Dysregulated complement mechanisms, such as those involving C5 components, contribute to the initiation and progression of several neuropathies." (PMID 33917266, 2021).
Opportunistic infection (1 paper, 2019). An infection that is caused by a pathogen that would generally not be able to cause an infection in a host with a normal immune system. "Nevertheless, the complement inhibiting effect of C5 blockers is often extensive and systematic, resulting in elevated risk of immunosuppression and opportunistic infections." (PMID 31752725, 2019).
pancreatitis (1 paper, 2017). Inflammation of the pancreas. "In genetically modified mice lacking either C5 or C5a receptor, cerulein-induced pancreatitis was characterized by a distinctly more severe clinical progression as compared to wild-type mice, with aggravated local pancreas as well as remote lung injury." (PMID 28144242, 2017).
periodontal disease (1 paper, 2021). "The complement factors C3 and C5 were previously identified as key players in periodontal disease." (PMID 33803323, 2021).
Peritoneal Fibrosis (1 paper, 2022). Disorder characterized by a wide range of structural changes in PERITONEUM, resulting from fibrogenic or inflammatory processes. "We demonstrate that the gene expression of the complement molecules (C2, C3, C5, C6) and the inhibitory molecules (CD55) is increased in the abdominal wall of the CHX-induced mouse model of peritoneal fibrosis." (PMID 36359246, 2022).
polyarticular arthritis (1 paper, 2010). An arthritis affecting five or more separate joints. "Using several polyarticular arthritis models, which all involve immune complexes and C5 activation, we showed here that u-PA is important for full disease expression." (PMID 20196869, 2010).